COL7A1 (collagen type VII alpha 1 chain)
Diseases named in the same sentence as COL7A1 in open-access papers (continued):
Sharing a sentence is not in itself a finding about the gene and the disease.
squamous cell carcinoma (8 papers, 2020 to 2025). A carcinoma arising from squamous epithelial cells. "Coding for type IV collagen, COL7A1 was also a risk factor to ccRCC survival according to our results, supported by a previous study revealing high expression of COL7A1 was associated with tumor invasion and shorter survival in several types of squamous cell cancer." (PMID 32789468, 2020). "Mutations in COL7A1 may contribute to intrinsic dysregulation of immune homoeostasis in RDEB patients, leading to systemic immune dysregulation and chronic inflammation, which can result in fibrosis and may be linked to the development of squamous cell carcinoma (SCC)." (PMID 39809737, 2025). "Intriguingly, COL7A1 was found to be significantly over-expressed in lung squamous cell carcinoma (LUSC), where the interaction between laminin 332 and COL7A1 might lead to the activation of the PI3K signaling pathway, ultimately contributing to squamous cell carcinoma." (PMID 40028167, 2025).
breast carcinoma (6 papers, 2014 to 2024). "Five PVs (1.2%) were found in the COL7A1 gene; among these patients, only two showed a family history of PC and breast cancer." (PMID 36139606, 2022). "In the human breast cancer cell lines, we showed that Smad3 binding to known target sites in the promoters of the SMAD7, COL7A1, and SERPINE1 genes in M3 cells was maximal by 1 hour after TGF-β addition, so this time point was selected for the ChIP-chip analysis." (PMID 24890385, 2014).
esophageal squamous cell carcinoma (4 papers, 2019 to 2025). Esophageal squamous cell carcinoma (ESCC) is a type of esophageal carcinoma (EC) that can affect any part of the esophagus, but is usually located in the upper or middle third. "For instance, COL7A1 was highly expressed in esophageal squamous cell carcinoma and significantly associated with the depth of tumor infiltration." (PMID 40028167, 2025). "The COL7A1 expression is correlated with tumor invasion and prognosis in esophageal squamous cell carcinoma." (PMID 35993054, 2022). "COL7A1 gene encodes for collagen type VII, and was found aberrantly expressed in esophageal squamous cell carcinoma." (PMID 34960256, 2021).
lung carcinoma (4 papers, 2019 to 2025). "As a BM-related prognostic marker, COL7A1 demonstrated strong prognostic performance and immune microenvironment predictive capacity in lung cancer." (PMID 41235257, 2025).
pulmonary fibrosis (4 papers, 2025). Chronic progressive interstitial lung disorder characterized by the replacement of the lung tissue by connective tissue, leading to progressive dyspnea, respiratory failure, or right heart failure. "Among the identified candidate genes, the COL6A3, COL7A1, WNT5B, and MMP3 have been demonstrated to be associated with pulmonary fibrosis." (PMID 40034336, 2025). "One potential explanation for the elevated COL7A1 mRNA expression and collagen VII protein deposition in the fibroblast foci may be dysregulated TGF-β signaling, which is the most powerful signaling pathway regulating ECM production and tissue remodeling in lung fibrosis." (PMID 40311757, 2025).
epidermolysis bullosa dystrophica (3 papers, 2019 to 2023). A genetic skin disorder caused by mutations in the type VII collagen gene (COL7A1). "In total, there were 11 unique P/LP variants in three genes related to three genetic diseases: COL7A1 AR Epidermolysis bullosa dystrophica, ABCA4 Stargardt disease type 1, and CFTR cystic fibrosis." (PMID 36635046, 2023).
Nail dystrophy (3 papers, 2021 to 2024). Onychodystrophy (nail dystrophy) refers to nail changes apart from changes of the color (nail dyschromia) and involves partial or complete disruption of the various keratinous layers of the nail plate. "Heterozygous missense mutations in the human COL7A1 gene – coding for collagen VII – lead to the rare, dominantly inherited skin disorder dominant dystrophic epidermolysis bullosa (DDEB), which is characterised by skin fragility, blistering, scarring and nail dystrophy." (PMID 34085701, 2021).
pancreatic cancer (3 papers, 2021 to 2025). "A total of 8 immune genes (ITGA7, RBM14, DENND4B, LQK1, ZNF709, COL7A1, SP1, NCBP2) were identified as independent prognostic factors of pancreatic cancer, which were used to construct a clinical predictive model." (PMID 33546693, 2021).
alopecia (2 papers, 2025). Hair loss usually from the scalp. "We highlight the importance of recognizing scarring alopecia as a complication of DEB, with discernment for concomitant inflammatory etiologies that may co-occur, especially in a patient with a COL7A1 mutation." (PMID 41523446, 2025).
Clear Cell Renal Cell Carcinoma (2 papers, 2023 to 2024). "Studies have shown that high COL7A1 expression is associated with poor prognosis in clear cell renal cell carcinoma (ccRCC), and in vitro knockdown of COL7A1 expression significantly affects the migratory ability of ccRCC cells." (PMID 38898429, 2024).
dominant dystrophic epidermolysis bullosa (2 papers, 2020 to 2021). "The COL7A1 gene encodes homotrimer fibrils essential for anchoring dermal and epidermal layers, and pathogenic mutations in COL7A1 can cause recessive or dominant dystrophic epidermolysis bullosa." (PMID 33081018, 2020).
fibrosis (2 papers, 2024 to 2025). the formation of excess fibrous connective tissue in an organ or tissue in a reparative or reactive process. "Interestingly, COL7A1 mRNA expression has also been demonstrated to be triggered by TGF-β1 in primary ATII cells, as well as by a fibrosis cocktail (containing TGF-β1 and other IPF-relevant cytokines) in ATII cells derived from human induced pluripotent stem cells." (PMID 40311757, 2025).
nail disorder (2 papers, 2019 to 2022). A disease involving the nail. "Pathogenic variants of five genes (RSPO4, FZD6, HPGD, PLCD1, and COL7A1) have been reported to cause congenital pure nail disorders, among which FZD6 (frizzled class receptor 6) and RSPO4 are responsible for most of the cases." (PMID 36421794, 2022). "Another gene related with nail disorders is COL7A1, which the alpha chain of type VII collagen that is associated with NDNC8 (OMIM 607523)." (PMID 30642273, 2019). "The genes associated with human hereditary nail disorders are listed as HPGD, RSPO4, PLCD1, COL7A1 and FZD6." (PMID 30642273, 2019).
renal cell carcinoma (2 papers, 2022 to 2023). "Overall, the incorporation of COL7A1 expression as a valid biomarker into increasingly personalized predictive tools may help to predict outcomes for patients with renal cell carcinoma." (PMID 37345040, 2023). "Third, although this study found that four genes (COL7A1, LCTL, NPR3, and ZFHX4), had a large impact on the prognosis of renal cell carcinoma and analyzed their relationship with survival in multiple cancers, the specific molecular biology and cell biology mechanisms need to be further investigated." (PMID 36159988, 2022).
sarcoma (2 papers, 2020 to 2022). A usually aggressive malignant neoplasm of the soft tissue or bone. "The 1-year AUC values for TCGA training cohort of the SAGRI constructed using the four sarcoma-like differentiation-related genes (COL7A1, LCTL, NPR3, ZFHX4) were 0.725 in the training set, 0.712 in the internal validation set, and 0.770 in the external validation set." (PMID 36159988, 2022).
Stroke (2 papers, 2024 to 2025). Sudden impairment of blood flow to a part of the brain due to occlusion or rupture of an artery to the brain. "Specifically, PPARα KO led to increased expression levels of Gadd45b, Nppa, Hdc, Lcn2, Il6, Sox4, Marcksl1, Saa3, Ucn2, Met, Dusp10, Elovl7, Ngf, C3, Il11, Hmox1, Alox5, Tnfsf9, Angptl4, Plin2, H19, Csf2rb, Atf3, and Col7a1 following stroke." (PMID 40362325, 2025).
AA amyloidosis (1 paper, 2025). Secondary amyloidosis is a form of amyloidosis, that complicates chronic inflammatory disorders (mainly rheumatoid arthritis) and is characterized by the aggregation and deposition of amyloid fibrils composed of serum amyloid A protein, an acute phase reactant. "While RDEB is caused by mutations in the COL7A1 gene, genetic predispositions beyond the primary mutation, such as polymorphisms in genes regulating inflammation and amyloid clearance, may also influence susceptibility to AA amyloidosis." (PMID 40630350, 2025).
adenoma (1 paper, 2025). A neoplasm arising from the epithelium. "Time series analysis using the likelihood ratios showed differences in expression of genes including Fos, Lama3, Aldh1a3, Col7a1 and Doks associated with increased induction by t = 12 h, whereas E2f8, Exo1, Clspn, Kif14 and Kif12 all were decreased in Smad4+/+ adenomas." (PMID 40348815, 2025).
aplasia cutis congenita (1 paper, 2024). Aplasia cutis congenita (ACC) is a rare skin disorder characterized by localized absence of skin that is usually located on the scalp but can occur anywhere on the body including the face, trunk and extremities. "Additionally, showed first-generation sequence and genetic results of the infant with heterozygous variations in the COL7A1 gene that might connect the development of Aplasia Cutis Congenita with chromosome 3 alterations." (PMID 38580989, 2024). "Furthermore, unlike our KRT14 patient, the COL7A1 patient had Aplasia cutis Congenita and skin absence at birth, which is a defining marker of DDEB." (PMID 38580989, 2024).
auditory neuropathy (1 paper, 2023). A hearing disorder characterized by impaired transmission of signals through the auditory nerve, resulting in mild to severe hearing loss and poor speech perception. "Mutations in COL7A1 were reported to potentially overlap with the TMIE gene that is involved in the mechanoelectrical transduction of cochlear hair cells and detected in a case of bilateral auditory neuropathy." (PMID 37273692, 2023).
bladder cancer (1 paper, 2024). "Unlike FAH and COL7A1, DICER1 has been directly investigated for its role in bladder cancer patients." (PMID 38580653, 2024).
Bradycardia (1 paper, 2022). A slower than normal heart rate (in adults, slower than 60 beats per minute). "Rhythm alterations were detected in 2 patients: bradycardia in a patient affected by EBS and tachycardia in a patient with EBD and COL7A1 mutation." (PMID 35379269, 2022).
cartilage disease (1 paper, 2022). Softening and degeneration of the CARTILAGE. "COL7A1 is rarely identified in previous cartilage diseases studies." (PMID 36010590, 2022).
Chronic renal failure (1 paper, 2021). "Chronic renal failure, post-streptococcal glomerulonephritis, IgA mesangial disease and renal amyloidosis have been reported in patients with the recessive forms of dystrophic EB, with COL7A1 mutations resulting in markedly reduced or abnormal type VII collagen." (PMID 34123558, 2021).
collagenopathies (1 paper, 2023). "The collagens with the strongest known disease association are COL2A1 and COL7A1, with 19 and 13 implicated collagenopathies, respectively." (PMID 37189830, 2023).
cystitis (1 paper, 2023). Inflammation of the urinary bladder. "Although Col7a1 has not been reported as a mediator of H2O2-induced cystitis, the results of increased Col7a1 expression in H2O2-induced cystitis mice are consistent because the bladder wall of H2O2-induced cystitis mice has been shown to have increased fibrosis." (PMID 37931000, 2023).
eczema (1 paper, 2025). "COL7A1 further supports skin integrity and regeneration, which is crucial for healing compromised skin affected by conditions like eczema and psoriasis." (PMID 39940662, 2025).
epidermolysis bullosa pruriginosa (1 paper, 2021). "Family 4 was diagnosed with epidermolysis bullosa pruriginosa, which is also a rare subtype of DEB caused by variants in the COL7A1 gene, the key structural protein of anchoring fibrils at the dermo-epidermal junction." (PMID 33921969, 2021).
hemophilia A (1 paper, 2020). The most common form of hemophilia characterized by spontaneous or prolonged hemorrhages due to factor VIII deficiency. "Hemophilia A (F8 coding sequence − 7 kb), DMD (Dystrophin coding sequence − 14 kb) and skin disease Recessive Dystrophic Epidermolysis Bullosa (COL7A1 coding sequence − 9 kb) are examples of diseases for which replacement corrections of dysfunctional large genes could yield clinical benefits." (PMID 32883366, 2020).
Hyperglycemia (1 paper, 2025). An increased concentration of glucose in the blood. "Chronic inflammation and hyperglycemia in diabetic skin drive injury-related gene expression in fibroblasts, including a COL7A1-expressing subpopulation." (PMID 40612951, 2025).
Hyperkeratosis (1 paper, 2024). Hyperkeratosis is a histopathological term defining a thickened stratum corneum and may be present in many different skin conditions, with many possible overlaps. "Unlike our COL7A1 patient, our KRT14 patient had extensive palmar and plantar hyperkeratosis." (PMID 38580989, 2024).
hypothyroidism (1 paper, 2022). Abnormally low levels of thyroid hormone. "Hypothyroidism was detected in 2 patients with EBD and COL7A1 mutation." (PMID 35379269, 2022).
leiomyoma (1 paper, 2008). A well-circumscribed benign smooth muscle neoplasm characterized by the presence of spindle cells with cigar-shaped nuclei, interlacing fascicles, and a whorled pattern. "Collagen 7A1 (COL7A1) gene expression was lower (0·51 ± 0·11-fold; P < 0·05) in leiomyoma cells in culture as compared to myometrial cells in the absence of ATRA exposure." (PMID 18248652, 2008).
melasma (1 paper, 2022). "TheWNT3A, EDN3, ESR2, PTG2, MMP1, and SOD2 genes were up-regulated, whereas the COL4A1, CSF2, DKK3, COL7A1, TIMP4, CCL2, and CDH11 genes were down-regulated in melasma skin fibroblasts when compared to the ones from adjacent healthy skin." (PMID 35840442, 2022). "There was an increase in MMP1 gene expression and a decrease in collagen IV, VII (COL4A1, COL7A1), and TIMP4 expression in fibroblasts isolated from melasma skin." (PMID 35840442, 2022).
osteoarthritis (1 paper, 2021). A noninflammatory degenerative joint disease occurring chiefly in older persons, characterized by degeneration of the articular cartilage, hypertrophy of bone at the margins and changes in the synovial membrane. "However, COL7A1 is also downregulated in articular cartilage and subcondral bone in the setting of osteoarthritis." (PMID 33974636, 2021).
prostate carcinoma (1 paper, 2019). A carcinoma that arises from epithelial cells of the prostate gland. "COL7A1 is highly expressed in CD133+/CD44+ prostate cancer spheroids." (PMID 31334229, 2019).
retinal detachment (1 paper, 2024). An eye emergency condition which may lead to blindness if left untreated. "There are no studies that specifically correlate FLG or COL7A1 dysfunction with retinal detachment." (PMID 39337590, 2024).
skin cancer (1 paper, 2022). "Indeed, the COL7A1 mutation detected in DEB patients has been related to chronic wounds, bacterial colonization, skin infections and skin cancer." (PMID 35379269, 2022).
stomach tumors (1 paper, 2022). "We evaluated COL7A1 protein expression by immunohistochemistry in a set of 10 stomach tumors from patients treated at Rhode Island Hospital." (PMID 35120467, 2022). "Immunohistochemistry and in situ hybridization tested expression of COL7A1 in stomach tumors." (PMID 35120467, 2022). "Because COL7A1 is not known to be expressed in normal stomach, or anywhere in the gastrointestinal tract, we wanted to confirm that COL7A1 protein was expressed in stomach tumors, and importantly determine if COL7A1 was expressed in cancer cells and not just in the stroma." (PMID 35120467, 2022).
Wilms tumor (1 paper, 2020). An embryonal neoplasm characterized by the presence of epithelial, mesenchymal, and blastema components. "We also reported germline loss of function of COL7A1 in four C-AYA patients with Wilms tumor." (PMID 32371905, 2020).
cancer (32 papers, 2017 to 2025). A tumor composed of atypical neoplastic, often pleomorphic cells that invade other tissues. "Other cancer-related genes, such as COL7A1, PRKAR1A, ERCC3, and MTAP, had variants with a conflicting interpretation of pathogenicity or VUS, or they were not reported in ClinVar." (PMID 32443704, 2020). "COL7A1 acted as a tumor progression determinant, possibly through its association to cancer stem cells development." (PMID 30473748, 2018). "Finally, the expression of COL7A1 was knockdown in cancer-associated fibroblasts (CAFs) in PC to explore its role in PC progression." (PMID 41235257, 2025). "Previous research has reported associations between COL7A1 and various cancers." (PMID 40028167, 2025). "Current evidence on COL7A1 in cancer progression remains limited and largely derived from bioinformatic studies." (PMID 41235257, 2025). "Increased expression of COL7A1 was also detected in highly metastatic cancer cell lines as well as in prostate cancer-initiating cell spheroids." (PMID 37345040, 2023). "Our research revealed that increased expression of the COL7A1 gene is correlated with an aggressive form of the cancer and improve patient survival assessment, complementing the clinical characteristics that are already in use for survival prediction." (PMID 37345040, 2023). "We showed that the genes encoding ANPEP, PROK2, CHP2, PTPRM, AREG, and COL7A1 were differentially expressed between SRC and PC carcinomas." (PMID 35626106, 2022). "Genes encoding ANPEP, PROK2, CHP2, PTPRM, AREG, and COL7A1 showed significant differential expression in SRC and PC carcinomas." (PMID 35626106, 2022). "As was reported, several hub collagen-related genes including FN1, IL6, COL4A4 and COL7A1 were involved in the progression and development of variable cancers." (PMID 34960256, 2021). "In the immunohistochemistry study, COL7A1 was more highly expressed in cancer tissue than in normal tissue (p = 0.001)." (PMID 34512204, 2021). "Fifty seven of the 200 patients had high COL7A1 scores (total score ≥ 8) in their cancer tissues (28.5%)." (PMID 34512204, 2021). "Signet ring cell type cancer frequently had intracellular expression of COL7A1, and cancers with intracellular expression showed high overall immunohistochemistry scores compared with cancers with only extracellular expression of COL7A1." (PMID 34512204, 2021). "Comparison of clinicopathologic characteristics categorized by high/low immunohistochemistry scores and the expression site of COL7A1 in cancer tissues." (PMID 34512204, 2021). "COL7A1 expression was denser in cancer tissue than in normal tissue, and most of that expression was found in the extracellular matrix." (PMID 34512204, 2021). "Multinomial logistic regression to predict distant metastasis (n = 20) using the clinicopathologic factors of patients whose cancer tissues were evaluated with COL7A1 immunohistochemistry (n = 200)." (PMID 34512204, 2021). "Patient M1 had three variants in cancer-related genes (PRKAR1A c.221G>A; COL7A1 c.7313C>G; and MTAP c.634T>C)." (PMID 32443704, 2020). "In our present study, COL7A1 mRNA levels were down-regulated in cancer tissues, and the COL7A1-UCN2 chimera generation mechanism circumvented TGF-β1’s tumor-suppressive effects and thereby promoted tumor invasion and proliferation." (PMID 29499655, 2018). "COL7A1 is associated with survival in many cancers; however, the prognostic value of COL7A1 expression as a standalone biomarker in ccRCC has not been investigated." (PMID 37345040, 2023). "In vitro knockdown of COL7A1 expression significantly affected ccRCC cells’ ability to migrate, leading to the hypothesis that COL7A1 may have a role in cancer aggressiveness." (PMID 37345040, 2023). "If the role of COL7A1 in ccRCC aggressiveness is confirmed, it may be an interesting therapeutic target, as it is for type I collagen in some cancer types." (PMID 37345040, 2023).